IL17RA (interleukin 17 receptor A)
Diseases named in the same sentence as IL17RA in open-access papers (continued):
Sharing a sentence is not in itself a finding about the gene and the disease.
rheumatoid arthritis (15 papers, 2013 to 2025). A chronic, systemic autoimmune disorder characterized by inflammation in the synovial membranes and articular surfaces. "IL-17RA rs4819554 was previously linked with response to etanercept in psoriatic arthritis, while IL-17RC rs708567 was associated with lupus arthritis and was described in Tunisians with rheumatoid arthritis." (PMID 34744511, 2021). "Moreover, HDAC3 has also been reported to negatively regulate miR-19a-3p to increase interleukin 17 receptor A (IL17RA) expression in rheumatoid arthritis (RA)-associated interstitial lung disease (ILD)." (PMID 35626663, 2022). "The aim of this study was to evaluate the safety, pharmacokinetics, and clinical response of brodalumab (AMG 827), a human, anti-IL-17 receptor A (IL-17RA) monoclonal antibody in subjects with moderate-to-severe rheumatoid arthritis (RA)." (PMID 24286136, 2013).
COVID-19 (13 papers, 2020 to 2025). A disease caused by infection with severe acute respiratory syndrome coronavirus 2. "Monocytes from patients with COVID-19 express high levels of genes associated with inflammation including IL17RA, JAK-STAT-associated gene STAT6, and inflammatory protein-encoding genes TNFRSF1B and ANXA2." (PMID 36992700, 2023). "Using curated genome-wide association study data, we found that individuals with genotypes corresponding to higher soluble IL17RA levels in plasma are at decreased risk of COVID-19 hospitalization." (PMID 33060197, 2020). "Accessory proteins such as the open reading frame 8 (ORF8) may be responsible for an increase in IL-17 driven inflammation in COVID-19 patients, as it has been shown to interact with the IL-17A receptor (IL17RA) and stimulate the IL-17 pathway, even in IL-17 deficient cells." (PMID 35572514, 2022). "Although Il-17A and IL-17F are known to signal through the same receptor IL-17RA/RC, the results obtained here from the analysis indicate that IL-17F and not IL-17A was significantly enriched in the plasma of patients with severe COVID-19." (PMID 39493750, 2024). "The increase of serum IL17RA prevents the interaction between IL-17 and its cell receptor, suggesting the benefit of monoclonal antibodies targeting the IL-17 pathway for COVID-19 treatment." (PMID 36481664, 2022). "Intriguingly, hsa-miR-29a-3p significantly downregulated in severe COVID-19 was predicted to bind the 3′-untranslated regions of both IL17RA and THBS1 mRNAs." (PMID 36481664, 2022). "This study repeatedly observed that IL17RA was consistently elevated in four different RNA-seq datasets profiling peripheral blood from severe COVID-19 patients, including a single-cell dataset." (PMID 36481664, 2022). "Based on RNA-Seq datasets, thrombospondin 1 (THBS1) and interleukin-17 receptor A (IL17RA) were significantly upregulated in severe COVID-19 patients’ blood." (PMID 36481664, 2022). "In general, the expression levels of IL17RA gene had significantly positive correlations with COVID-19 severity scores in CD14- positive monocytes (ρ = 0.474 and P = 0.0017) and neutrophils (ρ = 0.488 and P = 0.0016)." (PMID 36481664, 2022). "A sophisticated virus-host interaction analysis discovered that IL-17 receptor A (IL17RA) physically interacts with SARS-CoV-2 Orf8 protein, and highlighted a genetic locus associated with COVID-19 severity whose biological effects relate to IL-17 actions." (PMID 34646278, 2021). "Therefore, further studies in a large cohort are warranted to offer novel biomarkers and therapeutic options based on the THBS1, IL17RA, and miR-29a-3p for the treatment of severe COVID-19 patients." (PMID 36481664, 2022). "GO and KEGG pathway analyses showed that inflammation-, immunity-, and infection-associated terms were enriched in db/db mice microglia, such as Il17ra, Il6ra, Cmklr1, Nlrp3, Trem2, Coronavirus disease-COVID-19, Epstein-Barr virus infection, phagosome and NF-κB signaling pathway." (PMID 35721719, 2022). "Therefore, it is warranted to accumulate more data to understand the clinical relevance of IL17RA in the context of severe COVID-19 treatment." (PMID 36481664, 2022). "In addition, a future study with a large cohort analysis should clarify whether IL17RA is the molecular target of has-miR-29a-3p in the context of severity during COVID-19." (PMID 36481664, 2022). "To further validate the bioinformatics results, we performed qRT-PCR analysis for IL17RA and THBS1 in PBMC samples from COVID-19 patients (7 severe and 8 mild patients) and 8 healthy controls." (PMID 36481664, 2022). "Various studies suggested the inhibitory targeting of TH17, IL-17 or IL-17RA and the use of TH1 activators as potential therapeutic approaches for COVID-19." (PMID 34556132, 2021). "Moreover, elevated expression levels of IL17RA and THBS1 in the severe COVID-19 patients suggest that those genes could serve as indicators of COVID-19 severity." (PMID 36481664, 2022).
lung fibrosis (13 papers, 2011 to 2026). "Particularly, a research - examined lung biopsies from RA-ILD patients, supported that pathogenic fibroblasts overexpress IL-17A receptor (IL-17RA), in contrast to cells from either normal or idiopathic pulmonary fibrosis lung tissue." (PMID 39507540, 2024). "Importantly, IL-17 receptor A (IL17RA) is reported to play a direct role in lung fibrosis that may be particularly implicated in RA-ILD." (PMID 33343379, 2020). "In this study, a Bleomycin (BLM)-induced murine model of pulmonary fibrosis was used to study the effect of neutralization of IL-17RA and IL-17RC on ECM remodeling, MMPs, and the fibrinolytic system." (PMID 42298666, 2026). "Firstly, we measured the expression of HDAC3 and interleukin 17 receptor A (IL17RA) in lung tissue samples from normal controls, idiopathic pulmonary fibrosis (IPF) patients, and RA-ILD patients." (PMID 33343379, 2020). "Furthermore, IL-17 receptor A (IL17RA) is also reported to play a direct role in lung fibrosis." (PMID 37763769, 2023). "However, the researchers found IL-17A/IL-17RA axis was necessary for the production of TGF-β, a critical mediator of tissue remodeling and collagen deposition in pulmonary fibrosis." (PMID 33789737, 2021).
candidiasis (12 papers, 2013 to 2025). Infection with the organism Candida. "It is not yet clear to what extent therapeutic manipulation of the IL-17RA pathway will cause candidiasis, but this issue is obviously of clinical concern." (PMID 25849644, 2015). "Candidiasis often occurs in individuals with an inherited (gene mutations RORγ, RORγt, STAT3, TRAF3IP2, IL-17F, IL-17RA, IL-17RC) or acquired (drug-induced) dysregulation of IL-17." (PMID 40863217, 2025). "IL-17R is essential for immunity to OPC, whereas Il17ra−/− and Il17rc−/− mice are highly susceptible to oral mucosal Candida infection." (PMID 35628751, 2022). "Further studies of mice deficient in IL-17 and IL-23 via antibody-depletion also suggested the presence of IL-17RA-independent mechanisms of neutrophil recruitment in mucosal immunity against Candida infection." (PMID 29371568, 2017). "The cytokine IL-17 (IL-17A) and its receptor subunits, IL-17RA and IL-17RC, are required for protection to most forms of candidiasis." (PMID 25849644, 2015). "Subsequent work from our group and others showed that the IL-17RA subunit is essential for immunity to various forms of candidiasis, not only in experimental mouse models but also in humans with genetic predispositions to CMC." (PMID 25849644, 2015). "To assess whether the IL-17 pathway was involved in IL-23-dependent inhibition of myeloid cell apoptosis during systemic candidiasis, we infected Il17ra-/- mice and analyzed the viability of myeloid cells 48h post infection." (PMID 31887131, 2019). "Given the accumulating genetic evidence that the IL-17RA/RC complex is essential for protection from candidiasis, it is important to understand the potential adverse side effects of anti-IL-17/IL-17RA therapy on immune responses that protect against opportunistic infections." (PMID 25849644, 2015). "Congenital immunodeficiencies with candidiasis, T lymphocyte dysfunction, and IL-17 deficiency have been described in the context of pathogenic variants in genes such as STAT3, CARD9, DOCK8, ACT1, IL-17RC, IL-17RA, and IL-17F—where fluconazole is the first-line treatment." (PMID 40686918, 2025). "However, the absence of a difference in the overall number of viable Ly6Clo myeloid cells in the kidney of Il17ra-/- mice led us to conclude that the IL-17 pathway does not make a relevant contribution to the control of this myeloid cell subsets during systemic candidiasis." (PMID 31887131, 2019). "Additionally, untreated WT mice had a modestly increased survival benefit compared to bradykinin treated IL-17RA-/- mice, suggesting that there may also be a Bdkrb-independent pathway occurring in candidiasis." (PMID 27814401, 2016). "Although the importance of IL-17RA/RC was clear, IL-17RA is used by other ligands including IL-17C, leaving open the possibility that cytokines in addition to IL-17A might contribute to immunity to candidiasis." (PMID 25849644, 2015). "Our recent finding centered on Candida infection in oral epithelium showed neutrophil influx to the infection site is not exclusively modulated by IL-17RA, implying the involvement of additional genes." (PMID 29371568, 2017).
gastric cancer (12 papers, 2014 to 2026). A primary or metastatic malignant neoplasm involving the stomach. "Compared to wild-type mice, IL-17RA-deficient mice are more prone to developing gastric cancer, with more a severe disease progression." (PMID 40227215, 2025). "The IL‐17RA results for CRC are consistent with those for NSCLC, gastric cancer, and osteosarcoma, where high IL‐17RA expression was found to be associated with poor prognosis." (PMID 38491831, 2024). "The role of IL-17RA engagement in promoting tumor development and progression has been identified in gastric cancer, non-small cell lung cancer, and osteosarcoma 28-30." (PMID 41438576, 2026). "Nevertheless, it appears that IL-17RA and IL-17RC play opposite roles in the development of gastric cancer." (PMID 40227215, 2025). "Secondly, IL-17A also activates the NF-κB/NADPH oxidase 1 (NOX1) signaling pathway by binding to IL-17RA and IL-17RC, and promotes the cell cycle transition from G1 to S phase, thereby promoting the proliferation of gastric cancer cells." (PMID 39906741, 2024). "In this study, we investigated the role of IL-17RA in H. pylori induced gastric cancer using the InsGAS mouse model." (PMID 39588838, 2024). "Clinically this is relevant because higher IL-17RA expression is a favorable prognostic marker in gastric cancer." (PMID 39588838, 2024). "Chronic activation of T helper (Th) 1 and Th17 pathways contributes to prolonged inflammation; yet, higher expression of IL-17 receptor (IL-17RA) is a favorable prognostic marker for survival after gastric cancer diagnosis." (PMID 39588838, 2024). "The promotion of tumor development and progression owing to IL‐17RA engagement has been recognized for gastric cancer, non‐small cell lung cancer (NSCLC), and osteosarcoma." (PMID 38491831, 2024). "Together these data suggest that IL-17RA limits pathology and the development of dysplasia and gastric cancer." (PMID 39588838, 2024). "Our other protein that showed decrease in serum level after surgery, CREG (gastric cancer), IL-17RA (gastric/colorectal cancer), and PD-L2 (breast/liver cancer) have been associated with other cancers." (PMID 33274048, 2020). "By utilizing the open-access tool from the Human Protein Atlas and investigating whether expression of IL-17RA has any prognostic value, it is evident that IL-17RA expression is a favorable prognostic marker for stomach cancer survival (p < 0.001)." (PMID 38639570, 2024). "Overexpression of IL-17RA in gastric cancer (GC) tissue compared to normal adjacent tissues suggests its significant role in the progression, metastasis, and prognosis of gastric cancer may play an important role." (PMID 39906741, 2024). "Taken together, these data suggest IL-17RA is vital for controlling chronic inflammation in the gastric mucosa, ultimately reducing architectural changes in the tissue, reducing DNA damage, and slowing the development of H. pylori induced gastric cancer." (PMID 39588838, 2024). "IL‐17RA is overexpressed in several cancers, including gastric cancer, NSCLC, and osteosarcoma." (PMID 38491831, 2024). "In addition, immunohistochemical images from HPA indicated low levels of HRH4 protein and high levels of IL-17RA protein in gastric cancer tissues." (PMID 34367971, 2021). "Although many studies have highlighted that IL-17 and its downstream signaling pathways contribute to poor prognosis in various cancers, including osteosarcoma, NSCLC, gastric cancer, pancreatic carcinoma, and CRC, the impact of IL-17RA on CRC prognosis and progression remains debated." (PMID 41438576, 2026). "A clinical study found that IL-17RA rather than the other four members of the IL-17 receptor family is significantly upregulated in human gastric cancer tissues compared with normal gastric tissues." (PMID 37637418, 2023). "In addition, immunohistochemical images from HPA indicated high levels of IL-17RA protein and low levels of HRH4 protein in gastric cancer tissues." (PMID 34367971, 2021).
gastric cancer (continued). "Although numerous studies have shown that IL‐17A and its downstream signaling contribute to poor prognosis in several cancers, including osteosarcoma, NSCLC gastric cancer, pancreatic carcinoma and CRC,4, 10, 15, 16, 20 the role of IL‐17RA in tumor development and progression remains unclear." (PMID 38491831, 2024).
plaque psoriasis (12 papers, 2019 to 2025). "For reference, the ProLOGUE study—an open-label, multicenter, real-world randomized study in Japanese adults with plaque psoriasis treated with the IL-17RA inhibitor brodalumab via subcutaneous injection—reported a TSQM-9 satisfaction score of 83%." (PMID 41464777, 2025). "There are three anti-IL-17 monoclonal antibody agents which have approved by the US Food and Drug Administration for the treatment of moderate-to-severe plaque psoriasis: secukinumab and ixekizumab (IL-17 A antagonists), and brodalumab (IL-17RA antagonist)." (PMID 40055805, 2025). "Commercially available biologics for IL-25 exist in the form of brodamulab targeting the IL-25 receptor, IL-17 receptor A (IL-17RA), although this is limited to treating plaque psoriasis." (PMID 36311787, 2022). "Brodalumab, a recombinant fully human monoclonal IgG2 antibody with high affinity to human interleukin (IL)-17RA, is approved for the treatment of moderate to severe plaque psoriasis in adults." (PMID 36232430, 2022). "Brodalumab is a human interleukin-17 receptor A antagonist indicated for the treatment of moderate-to-severe plaque psoriasis in adult patients who are candidates for systemic therapy or phototherapy and have failed to respond or have lost response to other systemic therapies." (PMID 39589679, 2025).
Crohn disease (10 papers, 2014 to 2025). A gastrointestinal disorder characterized by chronic inflammation involving all layers of the intestinal wall, noncaseating granulomas affecting the intestinal wall and regional lymph nodes, and transmural fibrosis. "Clinical trials investigating neutralizing antibodies against IL-17 and IL-17-binding receptor (IL-17RA) in patients with Crohn’s disease revealed unexpectedly modest effectiveness." (PMID 40563358, 2025). "However, blocking IL-17A or IL-17RA is ineffective or even harmful in the treatment of Crohn's disease." (PMID 35528611, 2022). "However in Crohns disease blockade of IL-23 was effective while blockade of IL-17A or IL-17RA was not." (PMID 34552583, 2021).
breast cancer (9 papers, 2015 to 2026). A primary or metastatic malignant neoplasm involving the breast. "Here, we investigated the action of IL-17A and IL-17E on breast cancer cell lines and cell signaling events induced after recruitment of IL-17RA/IL-17RC or IL-17RA/IL-17RB receptors." (PMID 26154409, 2015). "In contrast IL-17E was reported to be produced by normal mammary epithelial cells, and its binding to IL-17RA-IL-17RB complex induced breast cancer cell apoptosis." (PMID 26154409, 2015). "IL17RA encodes for the Interleukin 17 Receptor A, a proinflammatory cytokine secreted by activated T-lymphocytes and, therefore, not essential for breast cancer cell homeostasis." (PMID 41366211, 2025). "Furthermore, the three IL-17R subunits, corresponding to the IL-17E (IL17RA/RB) and IL-17A (IL17 RA/RC) receptors, were highly upregulated in tumor versus normal samples, suggesting that IL-17E as IL-17A signaling is potentially active in human breast cancer." (PMID 26154409, 2015). "To address this question, we assessed the expression of IL-17E, IL-17RA, IL-17RC and IL-17RB in various human breast cancer cell lines as well as in non-transformed mammary epithelial cells MCF10A, in primary tumor cells (IJG-1731) derived ex vivo from an ER-negative breast cancer biopsy." (PMID 26154409, 2015).
emphysema (8 papers, 2011 to 2022). "Regarding other ligands for IL17RA, IL-25 has been reported to be associated with both Th2 and Th17 immune responses, however, little is known about the role of this cytokine in emphysema development." (PMID 23331548, 2013). "In contrast IL-17RA−/− mice showed significantly less tissue emphysema, which was also associated with a reduced mean linear intercept that approached the level of sham exposed mice." (PMID 21647421, 2011). "In vivo cigarette smoke induces CCL2 in the lung in an IL-17RA dependent manner, and IL-17RA is essential for smoke induced macrophage recruitment and emphysema." (PMID 21647421, 2011). "Taken together, these data suggest that IL-17RA expression may be affecting two independent processes that are required for the development of emphysema, namely macrophage recruitment via CCL2 and induction of MMP12 by CXCL10." (PMID 21647421, 2011). "Given the fact that IL-17 over expression increases CCL2 expression, we hypothesized that IL-17RA−/− mice would have reduced macrophage recruitment and reduced cigarette smoke induced emphysema." (PMID 21647421, 2011). "Taken together, these data demonstrate that cigarette smoke is a potent Th17 adjuvant and that IL-17RA signaling is required for chemokine expression necessary for MMP12 induction and tissue emphysema." (PMID 21647421, 2011). "Taken together these data demonstrate that cigarette smoke is a potent Th17 adjuvant and that IL-17RA signaling is required for the elaboration of CCL2, macrophage recruitment and tissue emphysema." (PMID 21647421, 2011). "After 6 months of cigarette smoke exposure we found that IL-17RA was critical for the induction of CCL2, macrophage recruitment, MMP12 expression, and emphysema in mice." (PMID 21647421, 2011). "Cigarette smoke seems to act as a selective adjuvant and enhance Th17 cell differentiation; mice lacking the IL-17 receptor A (IL-17RA) did not develop emphysema after a prolonged cigarette smoke exposure." (PMID 36293561, 2022). "In a mouse model, smoke exposed IL-17RA-/- mice failed to develop emphysema and anti-IL-17 antibodies attenuated airway inflammation in tobacco-smoke exposed mice." (PMID 26069967, 2015). "Immunoreactive IL-17A+ cells increase in frequency in the submucosa of COPD patients and IL-17A expression is elevated in CS exposure models, where mice lacking IL-17RA were protected from developing emphysema." (PMID 25405776, 2014). "Moreover, CS-exposed IL-17RA−/− mice failed to induce CCL2 (MCP1) and MMP12 and did not develop emphysema after 6 months of exposure." (PMID 26284585, 2016).